IL6 (interleukin 6)
Diseases named in the same sentence as IL6 in open-access papers (continued):
Sharing a sentence is not in itself a finding about the gene and the disease.
osteoporosis (continued). "Moreover, the elevated bone fracture risk, osteoporosis, and osteopenia were studied and confirmed to be present in chronic inflammatory disorders, due to the action of inflammation factors (such as IL-6, TNF, and IL-1β)." (PMID 35334519, 2022). "Osteoporosis caused by ovariectomy was not only mediated by overactivated osteoclast activity but inflammation, serological results indicated that dimemorfan also reduced IL‐1β, IL‐6, and TNF‐α secretion." (PMID 35611810, 2022). "Therefore, it is likely that H. pylori increases the risk of osteoporosis by promoting an inflammatory response to produce proosteoclastogenic cytokines such as TNFα, IL-1, IL-6, and IL-8." (PMID 35418807, 2022). "Of note, high IL‐6 concentration is linked with osteoporosis and angiogenesis in MM." (PMID 36444620, 2022). "In humans, IL-6 gene variants have been associated with osteoporosis and osteopenia." (PMID 35276096, 2022). "Genetic variants of IL-6 are one of the risk factors for osteoporosis." (PMID 36568096, 2022). "IL-6 affects bone loss and osteoporosis and plays an important role in bone reconstruction." (PMID 34671409, 2021). "IL-6 is an essential osteoclastogenic factor produced by neoplastic plasma cells in multiple myeloma and is also a major predictor of bone loss in menopausal osteoporosis." (PMID 32069819, 2020). "A total of 9 studies involving 1891 osteoporosis patients and 2027 healthy controls were included in the current meta-analysis, of which 8 studies evaluated the association between IL-6 174G/C polymorphism and osteoporosis, 3 studies related to IL-6 572C/G (rs1800796)." (PMID 32466786, 2020). "However, the IL-6 572C/G C allele was found to be associated with reduced susceptibility to osteoporosis (OR = 0.76, 95% CI: 0.56–1.04)." (PMID 32466786, 2020). "Our aim in this study was to examine whether the inhibitory effect of IL-6 on bone loss and skeletal pain associated with osteoporosis in hindlimb-unloaded (HU) mice in comparison with bisphosphonate." (PMID 32429268, 2020). "Clinically, enhanced IL-6 production is reported to be associated with osteoporosis." (PMID 27128729, 2016). "In fact, tumor necrosis factor a (TNF-α) and interleukin-6 (IL-6) have been reported to be associated with osteoporosis in COPD patients, and both factors are known to stimulate osteoclasts and increase bone resorption through RANKL-mediated bone resorption in vitro." (PMID 22360380, 2012). "In addition to the effect of cytokines such as IL-6 on the formation of total Periostin, the impact on the splice variants formed is of interest in assessing the function of Periostin in bone during inflammation and osteoporosis." (PMID 39940700, 2025). "This suggests that targeting IL-6 or its associated signaling pathways could offer a promising strategy for managing conditions characterized by excessive osteoclast activity, such as osteoporosis." (PMID 40895539, 2025). "Interestingly, IL-6 is also a cytokine associated with the inflammatory response in osteoporosis." (PMID 39074257, 2024). "The two IL6 variants, rs1800795 and rs1554606, reported in Egypt and Saudi Arabia, respectively, are considered unique to the Arab region according to genotype–phenotype correlation, as they were only reported in other ethnic populations with inflammatory conditions, such as osteoporosis in Taiwan." (PMID 34131278, 2021). "However, the IL-6 572C/G C allele was associated with reduced osteoporosis risk." (PMID 32466786, 2020). "Taken together, these results suggest a critical role for skeletal muscle lamin A/C to prevent cellular senescence, IL-6 expression, hyperosteoclastogenesis, and trabecular bone loss, uncovering a pathological mechanism underlying the link between muscle aging/senescence and osteoporosis." (PMID 32479501, 2020).
osteoporosis (continued). "The novelty of this research is that IL-6 is one of the causes of immobility-induced osteoporotic pain regardless of improvement of bone loss and the results may be useful as basic research on low back pain of long-standing disuse osteoporosis." (PMID 32429268, 2020). "In conclusion, IL-6 572C/G GG genotype may be associated with increased risk of osteoporosis." (PMID 32466786, 2020). "Finally, 9 studies met inclusion and exclusion criteria (involving 1891 osteoporosis patients and 2027 healthy controls), of which 8 studies explored the relationship between IL-6 174G/C (rs1800795) and osteoporosis, 3 studies reported IL-6 572C/G (rs1800796) and osteoporosis predisposition." (PMID 32466786, 2020). "Finally, our finding of the association of IL-6 with measures of bone health identifies a novel potential treatment target to prevent osteoporosis in CCS and requires prospective studies to determine what if any impact modification of this inflammatory variable will have on bone health in CCS." (PMID 22455440, 2012). "Collectively, these findings establish NF-κB p65 and PPARγ as experimentally validated hub targets of asiatic acid in osteoporosis, whereas direct modulation of IL-6 and STAT3 has remained insufficiently characterized." (PMID 41562931, 2026). "Network pharmacology identified key osteoporosis-related targets involved in inflammatory signaling, hormone regulation, and bone remodeling, with key hubs including IL-6, STAT3, NF-κB, and PPARγ." (PMID 41562931, 2026). "IL-6, one of the most representative inflammatory cytokines, has been observed to increase in blood concentrations in patients with osteoporosis and is known to promote bone resorption and simultaneously interfere with bone formation." (PMID 41179017, 2025). "Inflammatory mediators such as tumor necrosis factor-alpha (TNF-α), interleukin-1 beta (IL-1β), and interleukin-6 (IL-6), which are elevated in both osteoporosis and neurodegenerative diseases, serve as common mechanistic links." (PMID 41007423, 2025). "In summary, IL1RN and IL-6 inhibitors demonstrate substantial potential in treating a variety of immune-related diseases, particularly osteoporosis and Alzheimer's disease." (PMID 40153574, 2025). "Increased expression of IL-6 in patients with osteoporosis was detected; therefore, the effect of cytokines on Periostin splice variant expression was evaluated here." (PMID 39940700, 2025). "The bone-resorbing properties of Periostin and its interaction with IL-6 open up new possibilities for the pharmacological treatment of osteoporosis." (PMID 39940700, 2025). "Oxidative stress is a robust inducer for the expression of pro-resorptive cytokines such as IL-1, TNF-α, and IL-6, culminating in osteoporosis." (PMID 39780225, 2025). "A clinical study indicated that the degree of osteoporosis in patients with RA was positively correlated with IL-6 levels." (PMID 40291774, 2025). "Resveratrol promotes osteogenic differentiation by inhibiting apoptosis and regulating apoptosis-related proteins such as TNF and IL6, with potential implications for osteoporosis treatment." (PMID 40243497, 2025). "Osteoporosis involves chronic inflammatory responses where certain proinflammatory markers (e.g., tumor necrosis factor alpha, interleukin-1b, and interleukin-6) enhance osteoclast activity, reducing bone density." (PMID 41010472, 2025). "In obesity and T2DM, increased levels of pro-inflammatory cytokines like TNF-α and IL-6 lead to enhanced bone resorption and inhibit osteoblast differentiation, contributing to osteoporosis." (PMID 41007423, 2025). "IL-6 is known to promote RANKL and inhibit OPG, thus being associated with osteolysis, osteoporosis, RA, and other bone-related conditions." (PMID 38473934, 2024). "Another member of the interleukin family, interleukin 6 (IL-6), activates bone degradation, suggesting potential involvement in osteoporosis." (PMID 38540775, 2024).
osteoporosis (continued). "Polymorphisms associated with osteoporosis such as those in osteoprotegerin (OPG) and interleukin-6 (IL-6) were found to be associated only with lumber spinal BMD in cohorts with a relatively small sample size of AIS patients." (PMID 38275421, 2024). "Understanding the functions of IL-6 allows for the development of new strategies for the treatment and prevention of osteoporosis." (PMID 39200293, 2024). "Immune cells, cytokines, and chemokines play crucial roles in osteoporosis, with the immune system's effect on bone remodeling often manifested through B and T-cell activation, increased IL-17, IL-6, RANKL, TNF-α, and other pro-bone resorption factors." (PMID 38994021, 2024). "In osteoporosis, pro-inflammatory cytokines, such as IL-1, IL-6, IL-1β, and TNF-α, have been positively correlated with periodontal bone loss." (PMID 39410587, 2024). "Osteoporosis is a chronic inflammatory disease, in which pro-inflammatory cytokines including interleukin (IL)-1, tumor necrosis factor α (TNF-α), and IL-6 serve as primary mediators of the accelerated bone loss at estrogen deficiency." (PMID 37041523, 2023). "Previous studies have shown a correlation between chronic lung disease and osteoporosis, including an increase in inflammatory responses such as C-reactive protein and interleukin (IL)-6." (PMID 37240965, 2023). "There was a significant increase in IL-6 levels in the osteoporosis group compared to the control group in the current study." (PMID 37035758, 2023). "We established rat osteoporosis model with dexamethasone, and the ELISA assay showed that the serum IL-6 level increased greatly in dexamethasone group than the control group." (PMID 36750182, 2023). "In a mouse model of osteoporosis, the inflammatory state of the microenvironment inhibits the osteogenic differentiation of BMSCs, and IL-6 is one of the most significant factors in this inhibition." (PMID 37475866, 2023). "Inflammatory cell-induced cytokines, including matrix metalloproteinases, IL-6, IL-17, osteoprotegerin, and TNF-α, have been strongly associated with the development of osteoporosis." (PMID 37240965, 2023). "Applying IL-6 antagonists to transgenic mice with highly expressed IL-6 can prevent the occurrence of osteoporosis and growth retardation." (PMID 37035758, 2023). "In relation to osteoporosis, a correlation between IL-6 and skeletal pain was also observed, as the use of IL-6 inhibitors reduced pain in ovariectomized mice, although not restoring normal bone structure." (PMID 37238956, 2023). "AUC cut-off values (IGFBP-3: 3.65, IL-6: 0.205) were best evaluated for the diagnosis of postmenopausal women with osteoporosis, and the AUC for circulating IGFBP-3 and IL-6 were 0.706 (95% CI 0.594–0.818) and 0.685 (95% CI 0.571–0.798), respectively." (PMID 37035758, 2023). "Estradiol can also downregulate gp130 and IL-6 levels in mouse bone marrow, protecting against osteoporosis." (PMID 37828513, 2023). "Previous studies have provided support of an involvement of inflammatory cytokines, such as interleukin-6 and tumor necrosis factor, in the pathogenesis of osteoporosis." (PMID 37260443, 2023). "We found that the rat serum level of IL-6 was increased in the dexamethasone-induced osteoporosis model, and IL-6 expression was detectable in several progenitor cells and MEFs." (PMID 36750182, 2023). "Activation of inflammatory factors associated with osteoporosis such as TNF-α, NF-κB, IL-1, IL-6, and IL-17 has been to be involved in the physiology of pro-osteoclast formation." (PMID 36967748, 2023). "Actually, high serum concentrations of the inflammatory cytokines IL-6 and TNF-α have been associated with osteoporosis." (PMID 34842966, 2022). "A clinical study showed that IL6 mRNA was highly expressed in bone explants of patients with pyramidal fractures due to osteoporosis." (PMID 35479581, 2022).
osteoporosis (continued). "Bazedoxifene, approved by the Food and Drug Administration (FDA) as a selective estrogen modulator for osteoporosis treatment, has been demonstrated to be a new drug that inhibits the IL-6/gp130/STAT3 pathway." (PMID 35565185, 2022). "It is also necessary to investigate associations among inflammatory markers (IL-6, TNF-α, CRP), myosteatosis, blood lipid levels, adiposity, osteoporosis or osteopenia, bone demineralization and other comorbidities." (PMID 35330186, 2022). "In MM, overproducing proinflammatory cytokines, mainly Interleukin‐6 (IL‐6), leads to osteoporosis and angiogenesis." (PMID 36444620, 2022). "Production of IL-6 induces eminent lytic lesions along with diffuse osteoporosis typical of the disease." (PMID 35487926, 2022). "Elevated levels of proinflammatory cytokines such as tumor necrosis factor (TNF), interleukin 1 (IL-1), interleukin 6 (IL-6), or interleukin 17 (IL-17) are also characteristic of osteoporosis." (PMID 35955603, 2022). "Particularly, in an in vivo test, IL-6 aggravated the severity of osteoporosis, due to fewer osteoclasts and increased bone destruction; this suggests that IL-6 plays a pivotal role in alleviating osteoporotic inflammation reactions." (PMID 35723292, 2022). "An example of this is the overproduction of osteoclasts mediated by IL-6 being a cardinal pathophysiological change in sex-steroid induced osteoporosis." (PMID 34887836, 2021). "Among the pro-inflammatory mediators that play a major role in osteoporosis, IL-6, TNF-α, IFN-γ, IL-1β, and ROS are worth mentioning." (PMID 34421899, 2021). "Bazedoxifene, approved for use as a selective estrogen receptor modulator for treatment of osteoporosis, was recently shown to be a novel inhibitor of IL-6/gp130 protein-protein interactions." (PMID 34149710, 2021). "Serum Interleukin 6 (IL-6) is elevated in mastocytosis patients and correlates with severity of symptoms and the presence of osteoporosis." (PMID 33407701, 2021). "More genes like interleukin 6 (IL-6), vitamin D receptor (VDR), estrogen receptor (ESR), and calcitonin receptor (CTR) as well others were suggested to be associated with osteoporosis and bone density." (PMID 34938374, 2021). "In osteoporosis, estrogen deficiency leads to elevated levels of RANKL and inflammatory factors, including IL-6 and TNF-α." (PMID 34168561, 2021). "Another possible mechanism involves inflammatory cytokines, in that osteoporosis patients have elevated systemic levels of pro-inflammatory cytokines IL-1, IL-6, and TNF-α." (PMID 33807030, 2021). "IL-6 was identified as the main cytokine with a role in the pathogenesis of inflammatory-induced osteoporosis." (PMID 33917641, 2021). "IL6 is a cytokine that involved inflammation and infection responses and was reported to play a role in the pathogenesis of osteoporosis." (PMID 33478001, 2021). "LncRNA DANCR up-regulated in blood mononuclear cells promoted bone resorption through releasing TNF-α and IL-6 and finally resulted in osteoporosis." (PMID 35308164, 2021). "In osteoporosis, IL-6/STAT3 signaling is closely related to the differentiation of osteoclasts and RANKL expression in osteoblasts, which are regulators of bone homeostasis." (PMID 34833909, 2021). "It is generally recognized that proinflammatory cytokines including IL-6 play a pivotal role in the pathogenesis of bone metabolic diseases including osteoporosis." (PMID 33478532, 2021). "Inflammatory cytokines, including tumor necrosis factor-α, interleukin-1β, and interleukin-6, have been postulated to be involved in AD, PD, and osteoporosis." (PMID 34955816, 2021). "It has been reported that human peripheral-blood monocytes (PBMCs) from osteoporosis patients have 29–67% higher secretion of IL-1β, IL-6, and TNF-α in whole blood culture compared with healthy control subjects." (PMID 34917622, 2021).
osteoporosis (continued). "TNF-α and IL-6 have been shown to mediate inflammation, which contributes to bone resorption and osteoporosis through stimulation of osteoclast development and activity." (PMID 32999682, 2020). "For IL-6 572C/G (rs1800796), statistically significant elevated osteoporosis vulnerability was found in IL-6 572C/G additive model (OR = 2.25, 95% CI: 1.55–3.26), dominant model (OR = 1.42, 95% CI: 0.78–2.56) and recessive model (OR = 1.96, 95% CI: 1.36–2.83)." (PMID 32466786, 2020). "Age-dependent osteoporosis resulted in significant increase in serum levels of phosphate, bone specific alkaline phosphatase, hsCRP, IL-1β, IL-6, TNF-α, MDA, NO, and RANKL gene expression." (PMID 32532246, 2020). "The hyperproduction of pro-inflammatory cytokines belonging to the Th1 profile, such as TNF-α, IL-1, IL-6, IL-17, constitutes the background of both secondary and primary osteoporosis." (PMID 32069819, 2020). "It was previously reported that DANCR was upregulated in blood mononuclear cells from osteoporosis patients and increased bone resorption activity by secreting osteoclastogenic factors such as IL-6 and TNF-α23." (PMID 32778797, 2020). "Meta-analysis revealed an association between the GG genotype in the IL6 − 174G/C (rs1800795) polymorphism and low BMD, as well as increased risk of osteoporosis, in a Caucasian population." (PMID 30377780, 2019). "IL-1, IL-6 and TNF-α are strong inducers of bone resorption and subjects with highly expression of these cytokines are susceptible to develop osteoporosis." (PMID 30717716, 2019). "IL-6 also appears to be one of the central mediators of osteoclast activity, activates bone resorption pathways, supporting a crucial role in osteoporosis." (PMID 31301734, 2019). "Interleukin 6 (IL6) is another potential candidate gene with a number of functional polymorphisms, suggested as candidates associated with BMD and/or osteoporosis." (PMID 30377780, 2019). "Osteoporosis is also common in older and post-menopausal women due to a natural reduction in estrogen levels and high IL-6 levels, adding to increased osteoclastogenesis and pronounced osteopenia." (PMID 30671025, 2018). "IL6‐KO mice are protected against ovariectomy‐induced osteoporosis via a mechanism that prevents osteoclast activation." (PMID 29632817, 2018). "Nephrolithiasis has been demonstrated to accelerate bone loss; therefore, osteoporosis could be possibly attributed to either the presence of hypercalciuria or decreased dietary calcium intake, and elevated serum levels of inflammatory factors such as IL-1, IL-6 and TNF-α." (PMID 29996796, 2018). "Commonly, when chronic injury and/or inflammation occurs, it instigates overexpression of IL-6 within the BMM resulting in pro-osteoclastic pathways, osteopenia, osteoporosis, and an increased fracture risk." (PMID 30671025, 2018). "Our study provides a deeper insight into the pathophysiology of osteoporosis and identifies IL-6 as a promising target for osteoporosis therapy." (PMID 27128729, 2016). "Our study provides deeper insight into the pathophysiology of osteoporosis and identifies IL-6 as a promising target for the treatment of osteoporosis." (PMID 27128729, 2016). "Our understanding of the precise molecular mechanisms and functional impact of inhibition of Wnt signaling pathway by IL-6 is crucial for proper understanding of its role in the RA and osteoporosis pathogenesis and progression." (PMID 27106351, 2016). "In clinical practice, upregulated expression of IL-6 has been reportedin the bone samples of postmenopausal women with osteoporosis." (PMID 25923459, 2015). "IL-6 is one of the most potent stimulators of osteoclastic bone resorption and central to the pathogenesis of generalized osteoporosis in RA." (PMID 26103626, 2015). "Increased production of IL-11, IL-6, and Rank L ameliorated the imbalance between bone absorption and formation, resulting in the prevention of osteoporosis in SAMP6." (PMID 25364723, 2014).